MROH9 (maestro heat like repeat family member 9)
Synonyms: C1orf129; FLJ23550; ARMC11
Tractability: No criterion of Open Targets' tractability assessment is met for any kind of drug.
Gene: Protein-coding gene on chromosome 1 (170,935,429 to 171,064,765, forward strand). Ensembl gene ENSG00000117501.
Genetic constraint (gnomAD): Loss-of-function variants: 66 observed, 66.16 expected, observed/expected ratio (o/e) 1, 90% interval 0.82 to 1.22. The upper end of that interval is the gene's LOEUF score, 1.22, which puts it in group 5 of 6, group 1 being the genes least tolerant of losing a copy. Missense variants: 819 observed, 814.09 expected, observed/expected ratio (o/e) 1.01, 90% interval 0.95 to 1.07. Synonymous variants: 322 observed, 301.69 expected, observed/expected ratio (o/e) 1.07, 90% interval 0.97 to 1.17.
Homologues: Orthologues: chimpanzee MROH9 (98% identical), macaque MROH9 (89% identical), rabbit MROH9 (69% identical), pig MROH9 (67% identical), dog MROH9 (65% identical), rat Mroh9 (58% identical), mouse Mroh9 (58% identical). Paralogues in human: MROH1 (20% identical), MROH5 (19% identical), MROH7 (19% identical), MROH8 (19% identical), MROH2B (16% identical), MROH6 (15% identical), MROH2A (15% identical), MRO (5% identical).
Diseases named in the same sentence as MROH9 in open-access papers:
MROH9 is named in the same sentence as 3 diseases in open-access papers, as found by Europe PMC text mining. Sharing a sentence is not in itself a finding about the gene and the disease. The quoted sentences say what the papers report.
trimethylaminuria (1 paper, 2024). A rare inborn error of metabolism characterized by the presence of large amounts of trimethylamine in urine, sweat, and breath, resulting in a fishy body odor in affected individuals. "The duplicated regions harbor a total of five protein-coding genes: MROH9 and members of the flavin-containing monooxygenase family, including FMO3 (mutations cause the recessive disorder Trimethylaminuria; MIM 602079), FMO2, FMO1, and FMO4, all located within the chr1_D region." (PMID 39257002, 2024).
cancer (1 paper, 2022). A tumor composed of atypical neoplastic, often pleomorphic cells that invade other tissues. "MET, AM25C, MROH9, MYEOV, FAM111B, Y6D, and PPP2R3A were highly expressed in the high-risk group, indicating that these genes may be related to the oncology process for patients with PAAD, and they seemed to be cancer-promoting genes." (PMID 35077391, 2022).
MROH9 also shares sentences with these, for which no sentence is quoted: pancreatic adenocarcinoma (1 paper).